AQP2 (aquaporin 2)
Description:
Forms a water-specific channel that provides the plasma membranes of renal collecting duct with high permeability to water, thereby permitting water to move in the direction of an osmotic gradient. Plays an essential role in renal water homeostasis. Could also be permeable to glycerol.
Synonyms: AQP-2; AQP-CD; NDI2; WCH-CD
Tractability: Antibody: UniProt places it where antibodies can reach, with high confidence; its Gene Ontology location is reachable by antibodies, with high confidence; UniProt predicts a signal peptide or a membrane-spanning region. PROTAC: ubiquitination databases record sites on it.
Target class: Ion channel; Other ion channel; Aquaporin; Water-specific aquaporin
Safety:
Unwanted effects reported when the protein is acted on. In parentheses: how it was acted on, where the effect was seen, and who reports it.
edema (source: ClinPGx)
Gene: Protein-coding gene on chromosome 12 (49,950,737 to 49,958,878, forward strand). Ensembl gene ENSG00000167580.
Subcellular location: Apical cell membrane; Basolateral cell membrane; Cell membrane; Cytoplasmic vesicle membrane; Golgi apparatus, trans-Golgi network membrane
Pathways (Reactome):
Transport of small molecules: Passive transport by Aquaporins; Vasopressin regulates renal water homeostasis via Aquaporins
Gene Ontology:
Molecular function: glycerol transmembrane transporter activity; protein binding; water channel activity; water transmembrane transporter activity; channel activity
Biological process: actin filament organization; cellular response to copper ion; cellular response to mercury ion; glycerol transmembrane transport; protein homotetramerization; renal water homeostasis; water transport; metanephric collecting duct development; transmembrane transport
Cellular component: apical plasma membrane; cytoplasmic vesicle membrane; extracellular exosome; membrane; plasma membrane; basolateral plasma membrane; transport vesicle membrane; cytoplasm; cytoplasmic vesicle; Golgi apparatus; lumenal side of membrane; perinuclear region of cytoplasm; recycling endosome
Genetic constraint (gnomAD): Loss-of-function variants: 20 observed, 21.13 expected, observed/expected ratio (o/e) 0.95, 90% interval 0.67 to 1.38. The upper end of that interval is the gene's LOEUF score, 1.38, which puts it in group 5 of 6, group 1 being the genes least tolerant of losing a copy. Missense variants: 325 observed, 360.15 expected, observed/expected ratio (o/e) 0.9, 90% interval 0.82 to 0.99. Synonymous variants: 168 observed, 166.07 expected, observed/expected ratio (o/e) 1.01, 90% interval 0.89 to 1.15.
Homologues: Orthologues: chimpanzee AQP2 (99% identical), macaque AQP2 (99% identical), dog AQP2 (96% identical), pig AQP2 (96% identical), guinea pig AQP2 (92% identical), rat Aqp2 (90% identical), mouse Aqp2 (89% identical), rabbit AQP2 (83% identical), tropical clawed frog aqp2 (54% identical), Drosophila melanogaster Drip (34% identical), Drosophila melanogaster Eglp4 (28% identical), Drosophila melanogaster Eglp2 (28% identical), and 3 more. Paralogues in human: AQP5 (64% identical), MIP (59% identical), AQP6 (57% identical), AQP4 (46% identical), AQP1 (44% identical), AQP7 (29% identical), AQP8 (28% identical), AQP9 (28% identical), AQP3 (27% identical), AQP7B (27% identical), AQP10 (23% identical).
Diseases named in the same sentence as AQP2 in open-access papers:
AQP2 is named in the same sentence as 160 diseases in open-access papers, as found by Europe PMC text mining. Sharing a sentence is not in itself a finding about the gene and the disease. The quoted sentences say what the papers report.
nephrogenic diabetes insipidus (63 papers, 2008 to 2025). Nephrogenic diabetes insipidus (NDI) is characterized by polyuria with polydipsia, recurrent bouts of fever, constipation, and acute hypernatremic dehydration after birth that may cause neurological sequelae. "Nephrogenic diabetes insipidus (NDI) is the result of the resistance of the kidneys to AVP due to mutations in the gene-encoding AVP receptor 2 (AVPR2) or aquaporin 2 (AQP2), adverse drug effects, or electrolyte disorders." (PMID 39941427, 2025). "AQP2 gene deletion or mutation leads to severe water imbalance and can result in nephrogenic diabetes insipidus." (PMID 39768394, 2024). "In humans, mutations in AQP2 are associated with nephrogenic diabetes insipidus, a form of polyuria resulting from impaired urine concentrating ability, suggesting the importance of AQP2 in urine volume regulation." (PMID 39609591, 2024). "For example, mutations in AQP2 can lead to non-X-linked nephrogenic diabetes insipidus (NDI), a condition with an extremely low incidence (~1 in 20 million births)." (PMID 37762642, 2023). "Impairments of AQP2 result in various water balance disorders, including nephrogenic diabetes insipidus (NDI), which is a disease characterized by a massive loss of water through the kidney and consequent severe dehydration." (PMID 34884753, 2021). "Mutations to AQP2 induce nephrogenic diabetes insipidus (NDI), where low/inactive water channels cause large urinary waste of possible fatal outcome." (PMID 34120413, 2021). "AQP2 mutation leads to nephrogenic diabetes insipidus (NDI), characterized by polyuria, polydipsia, and hypernatremia." (PMID 34512542, 2021). "In humans, mutations in the SPA-1 binding region in the C-terminus of AQP2 cause nephrogenic diabetes insipidus (NDI), a disease characterized by a massive loss of water through the kidney." (PMID 34884753, 2021). "Disease‐causing AQP2 mutations induce nephrogenic diabetes insipidus (NDI), a condition that challenges the bodily water balance by producing large urinary volumes." (PMID 34120413, 2021). "Deletion or mutation of the AQP2 gene causes severe water disorders and triggers the initiation of nephrogenic diabetes insipidus (NDI)." (PMID 30654539, 2019). "It frequently results in nephrogenic diabetes insipidus, similar to loss-of-function mutations in AQP2 (see Section 7.1)." (PMID 31027200, 2019). "On the other hand, a knock-in mutation of AQP2, a gene implicated in hereditary non-X-linked nephrogenic diabetes insipidus, causes more severe phenotypes in mice than in human subjects." (PMID 31549961, 2019). "Disruption of the renal AVPR2/AQP2 pathway can cause nephrogenic diabetes insipidus (NDI) characterized by the inability to concentrate urine." (PMID 29117938, 2018). "Loss of function mutations in human AQP0 cause congenital cataracts and AQP2 causes nephrogenic diabetes insipidus." (PMID 30555637, 2018). "Mutations in both the V2R and AQP2 itself result in significant polyuria, a disease known as nephrogenic diabetes insipidus." (PMID 29354070, 2017). "AQP2 for example, plays a critical role in water resorption in the kidney and mutations in the AQP2 gene cause kidney dysfunction and development of the disease nephrogenic diabetes insipidus." (PMID 28715506, 2017). "Aqp2 mutations in humans cause nephrogenic diabetes insipidus, a disease where water resorption by the collecing duct is eliminated." (PMID 23704941, 2013). "Inherited central and nephrogenic diabetes insipidus are primarily due to the decreased expression of AQP2 while mutation in the AQP2 molecule is responsible for inherited central diabetes insipidus." (PMID 20142913, 2008). "In acquired causes of nephrogenic diabetes insipidus, there is a downregulation of AQP2 expression in the inner medulla of the kidney." (PMID 20142913, 2008).
nephrogenic diabetes insipidus (continued). "Moreover, the mutation of Q57 or A147 (which is close to the cation fixation site) has been identified in patients suffering from nephrogenic diabetes insipidus, a disorder caused by the failure to address AQP2 to the apical membrane." (PMID 39194687, 2024). "Modulation of AQPs, such as restoring AQP1 and AQP3 levels or function or stabilizing AQP2 to enhance water reabsorption, could prove beneficial in the treatment of loss-of-function aquaporin diseases such as nephrogenic diabetes insipidus (NDI), among others." (PMID 39768394, 2024). "Point mutations in the gene for AQP2 may disturb this process and lead to nephrogenic diabetes insipidus (NDI), whereby patients void large volumes of highly hypo-osmotic urine." (PMID 37674034, 2023). "Natural mutations in AQP2 are responsible for nephrogenic diabetes insipidus (NDI), a condition where affected individuals are unable to concentrate ultrafiltrate, thus producing large urinary volumes, with corollary health problems including polydipsia, polyuria, dehydration and possibly death." (PMID 34120413, 2021). "Mutation or functional deficiency of AQP2 leads to severe nephrogenic diabetes insipidus." (PMID 30654539, 2019). "Loss-of-function mutations in AQP2 may provoke nephrogenic diabetes insipidus, a condition with excessive urine production frequently resulting in electrolyte imbalance." (PMID 31027200, 2019). "In mouse models of nephrogenic diabetes insipidus, collecting ducts are resistant towards vasopressin owing to V2 mutations, exaggerated phosphodiesterase-mediated AC degradation, interference with AC activity, or AQP2 deficiency or malfunction." (PMID 30271659, 2018). "Earlier we reported that the recombinant soluble (pro) renin receptor sPRR‐His upregulates renal aquoporin‐2 (AQP2) expression, and attenuates polyuria associated with nephrogenic diabetes insipidus (NDI) induced by vasopressin type 2 receptor (V2R) antagonism." (PMID 29138356, 2017). "In addition, Li may cause nephrogenic diabetes insipidus by inhibiting the expression of aquaporin channels, mainly aquaporin 2, in the renal collecting tubules, potentially leading to hypercalcemia through dehydration." (PMID 40747083, 2025). "In this case, the patient exhibited features suggestive of nephrogenic diabetes insipidus (NDI), a condition commonly associated with chronic lithium use due to its downregulation of aquaporin-2 channels in the renal collecting ducts." (PMID 40851725, 2025). "Chronic lithium treatment is associated with the development of nephrogenic diabetes insipidus (NDI), which is associated with AQP2 downregulation." (PMID 39194687, 2024). "And the down-regulation of AQP2 and UT-A1 pronouncedly elevated the urine output in lithium-induced nephrogenic diabetes insipidus." (PMID 37187875, 2023). "Dysregulation of miR-8114 facilitates the epigenetic regulation of AQP2 and results in nephrogenic diabetes insipidus." (PMID 36457055, 2022). "“Vasopressin escape” is similar to nephrogenic diabetes insipidus (NDI) in terms of the unresponsiveness of AQP2 to vasopressin." (PMID 32560242, 2020). "Our data provide a potential explanation to lithium-induced nephrogenic diabetes insipidus where lithium reduces Elf3 and hence AQP2 abundance." (PMID 31681015, 2019). "Consistently, we previously demonstrated that tamoxifen (TAM), a selective estrogen receptor modulator, attenuates the downregulation of AQP2 in lithium-induced nephrogenic diabetes insipidus (NDI)." (PMID 31447686, 2019). "They affect AQP2, AQP5 and AQP8, where they are associated with nephrogenic diabetes insipidus, keratoderma and colorectal cancer, respectively." (PMID 29799470, 2018).
nephrogenic diabetes insipidus (continued). "Hence, the results point to a resistance of collecting tubules towards vasopressin resulting in a loss of aquaporin-2 expression and adaptive hypertrophy to handle the increased rates of glomerular filtration and tubular reabsorption that occur in models of central or nephrogenic diabetes insipidus." (PMID 30271659, 2018). "Decreased AQP2 expression, manifested in nephrogenic diabetes insipidus (NDI), leads to an inability to maximally concentrate urine." (PMID 23258995, 2012). "However, lithium’s renal effects, particularly its impact on aquaporin-2 expression, can result in nephrogenic diabetes insipidus, contributing to disturbances in sodium and water balance independent of parathyroid function." (PMID 40851725, 2025). "A few classical disease-causing examples of this type include missense mutations in Aquaporin-2, cystic fibrosis transmembrane conductance regulator (CFTR), and insulin receptor, which lead to nephrogenic diabetes insipidus, cystic fibrosis and diabetes mellitus, respectively." (PMID 34359917, 2021). "In line with this, we have recently demonstrated that a selective estrogen receptor modulator (SERM), i.e., tamoxifen (TAM), attenuates the downregulation of AQP2 protein expression and improves urinary concentration in rats with lithium-induced nephrogenic diabetes insipidus (NDI)." (PMID 31447686, 2019). "Mutations of either AVPR2 or AQP2 result in a genetic disease known as nephrogenic diabetes insipidus, which is characterized by the lack of responsiveness of the collecting duct to the antidiuretic action of AVP." (PMID 29125546, 2017). "By up-regulating the expression levels of AQP2, statins increase water reabsorption by the kidney, thus opening up a new avenue in treating patients with nephrogenic diabetes insipidus (NDI), a hereditary disease that yet lacks high-powered and limited side effects therapy." (PMID 25594563, 2015). "They suggested that the beneficial effect of compounds of the cGMP pathway to relieve nephrogenic diabetes insipidus may be improved when combined with agents that stimulate AQP2 expression." (PMID 25111608, 2014). "The water-conserving role of AQP2 is now well documented in the renal collecting ducts of each of the three extant clades of Tetrapoda, but its evolutionary significance becomes manifest in humans with nephrogenic diabetes insipidus." (PMID 25426855, 2014). "Because decreased abundance of AQP2 in the kidney is sufficient to produce the urinary concentrating defect, the inability to adequately respond to augmented vasopressin-V2R axis can result in production of large volumes of dilute urine, such as occurs in nephrogenic diabetes insipidus." (PMID 30941057, 2019). "Downregulation of AQP2 and AQP3 is also common in several types of nephrogenic diabetes insipidus (NDI)." (PMID 38791455, 2024). "In certain acquired forms of nephrogenic diabetes insipidus (NDI), for example hypokalemia- or hypercalcemia-induced NDI, AQP2 is degraded via autophagy." (PMID 30901874, 2019). "11β-HSD2 null mice develop nephrogenic diabetes insipidus (NDI) with sodium wasting, increased diuresis and polydipsia, and reduced urine osmolality and AQP2 expression." (PMID 31863073, 2019). "In particular, age-associated nephrogenic diabetes insipidus in some inbred mouse strains and WAG/Rij rats are caused by an age-progressive decline of AQP2 suggesting that progranulin deficiency may lead to similar but premature AQP2 losses and hence, early manifestations of kidney aging." (PMID 30271659, 2018). "The most common adverse effect is nephrogenic diabetes insipidus (NDI), due to a decreased expression of the aquaporin-2 (AQP-2) water channel and incorrect trafficking of AQP-2 to the luminal membrane in collecting duct cells." (PMID 26441681, 2015).
nephrogenic diabetes insipidus (continued). "This review will summarize aspects related to water balance, renal AQP2, vasopressin and nephrogenic diabetes insipidus (NDI), as well as current treatment of NDI and possible use of statins with respect to AQP2 trafficking." (PMID 25594563, 2015). "In accordance with nephrogenic diabetes insipidus, untreated 4-month-old Col4a1 mutant mice did not have elevated levels of the water channel aquaporin 2 (Aqp2) that plays a crucial role in tubular water reabsorption and urine concentration." (PMID 26839400, 2016).
Polyuria (50 papers, 2008 to 2026). An increased rate of urine production. "Adenine-induced AQP2 downregulation in the outer and inner medullary collecting duct causes water wasting (polyuria), which is compensated for with an increase in water intake (polydipsia), allowing the animals to maintain a normal blood volume status." (PMID 40794384, 2025). "The presence of natriuresis and the transient character of the disease help to distinguish primary NDI due to mutations in the AQP2 channel and vasopressin-receptor 2 gene from lithium-induced polyuria." (PMID 36011745, 2022). "One apparent side effect in the kidneys is lithium-induced diabetes insipidus characterized with polyuria and polydipsia associated with reduced AQP2 gene expression." (PMID 31681015, 2019). "These mice display a complex phenotype, with increased activation of the thiazide-sensitive Na+-Cl− cotransporter (NCC), and polyuria due to a loss of aquaporin-2 (AQP2)." (PMID 30872636, 2019). "Lithium-induced NDI is associated with polyuria caused by marked downregulation of aquaporin 2 (AQP2) and AQP3 proteins." (PMID 30050465, 2018). "Col4a1 mutations also cause diabetes insipidus, whereby the tubular defects lead to polyuria associated with medullary atrophy and a subsequent reduction in the ability to upregulate aquaporin 2 and concentrate urine." (PMID 26839400, 2016). "In certain pathological states which trigger the development of polyuria, such as diabetes, decreased NO levels would lead to a reduction in the expression of AQP2 in order to avoid an excessive loss of water." (PMID 25111608, 2014). "Reduced expression and/or apical localization of Aqp2 under pathological conditions (i.e. nephrosis, hypokalemia, and Aqp2 mutations) results in polyuria." (PMID 23326416, 2013). "Combination of VDD and AmB/LE resulted in a more severe polyuria associated with lower protein expression of AQP2, suggesting that VDD might have exacerbated renal concentrating defect in AmB/LE-induced renal toxicity." (PMID 31295336, 2019). "Patients that receive lithium therapy develop polyuria associated NDI that might be secondary to downregulation of renal AQP2." (PMID 29138356, 2017). "Mice with Dot1l deficiency in renal Aqp2-expressing cells (Dot1lAC) develop polyuria by unknown mechanisms." (PMID 23326416, 2013). "The apparent discrepancy of high baseline AQP2 excretion associated with mild 24 h polyuria might be due to a reduced cortico-medullary gradient in hypercalciurics." (PMID 22403735, 2012). "In conclusion, we report that HUA can damage urine concentration capacity leading to a polyuria phenotype via down-regulating AQP2, AQP3 and AQP4 expression in the kidney." (PMID 40271210, 2025). "We revealed that patients and mice with HUA had a polyuria phenotype and found that the expression of aquaporin 2 (AQP2), AQP3 and AQP4 were significantly reduced in the kidneys of mice with HUA." (PMID 40271210, 2025). "Deposition of calcium in the medulla and downregulation of aquaporin 2 (AQP2) channels in collecting ducts result in dysregulated urine concentration that can be demonstrated in patients as polyuria and dehydration." (PMID 38920679, 2024). "In vivo, we found that β3‐AR−/− mice show mild polyuria and reduced urine osmolarity compared to wt mice, paralleled by reduced plasma membrane expression of AQP2 and reduced phosphorylation of NKCC217 and NCC." (PMID 38652212, 2024). "Urine AQP2 excretion in dogs can still be used as a prognostic tool to differentiate polyuria diseases such as central or NDI, inappropriate arginine vasopressin protein release, and primary polydipsia." (PMID 34903939, 2021). "Renal unresponsiveness to the antidiuretic hormone vasopressin impairs aquaporin-2 (AQP2) water channel activity and water reabsorption from urine, resulting in polyuria." (PMID 34224008, 2021).